TREM1 (triggering receptor expressed on myeloid cells 1)
Diseases named in the same sentence as TREM1 in open-access papers (continued):
Sharing a sentence is not in itself a finding about the gene and the disease.
glioblastoma (continued). "Our work presents novel pharmacological opportunities for inhibition of the TREM1+-myeloid-derived glioblastoma microenvironment with a recently discovered inhibitor of HuR dimerization SRI42127." (PMID 36249290, 2022). "A grade-dependent enhancement of the TREM1/HMGB1 axis in the glioblastoma microenvironment compared to normal brains was confirmed using clinical tissue samples and western blot technique." (PMID 36249290, 2022). "Glioblastoma patient-derived orthotopic xenografts should also be employed to verify that blocking TREM1 could decrease tumor-promoting effects of monocytes/TAMs." (PMID 38370418, 2024). "The TREM1+-myeloid-derived cell fusogenicity with glioblastoma cells and pro-inflammatory ability might have a profound impact on transformed cell plasticity, proliferation, immune evasion, metastasis, and development of drug resistance." (PMID 36249290, 2022). "Therefore, our results confirm involvement of the myeloid-derived microenvironment in cell fusion and spatial accumulation of TREM1+-cells in the peri-necrotic glioblastoma loci." (PMID 36249290, 2022). "Therefore, our results confirm the reduction of the HuR- and TREM1-dependent axis of cell fusion between glioblastoma neurospheres and myeloid-derived cells (neutrophils and Mφ) by the inhibitor of HuR dimerization SRI42127." (PMID 36249290, 2022). "Therefore, data analysis suggests that the TREM1+-microenvironment supports glioma progression and is enhanced with tumor grade and glioblastoma recurrence." (PMID 36249290, 2022). "The mini-ontology analysis of TREM1-dependent cell signaling pathways and transcripts expressed in gliomas of different grades based on data from the R2: platform confirmed a significant TREM1-influence on cell cycle progression in glioblastoma." (PMID 36249290, 2022). "TREM1+-microenvironment is enriched in glioblastoma peri-necrotic zones." (PMID 36249290, 2022). "Our analysis of expression profiles from four independent glioblastoma datasets suggests that hypoxia may induce TREM1, TNFAIP3 and BIRC3 in the inflammatory compartment." (PMID 19536297, 2009). "In addition, previous studies have shown that TREM1 may play a role in the immunobiological processes of glioblastoma." (PMID 41394801, 2025). "Therefore, our results confirm that the TREM1+-myeloid-derived microenvironment in the glioblastoma mouse models is mostly represented by PMN and Mφ; the inhibitor of the HuR dimerization might suppress it." (PMID 36249290, 2022). "We furthermore examined TREM1 protein expression in images of immunostained GBM samples stored in the Ivy Glioblastoma Atlas Project, which is a foundational resource for exploring the anatomic and genetic basis of GBM at the cellular and molecular levels." (PMID 32765489, 2020). "Ex vivo gas plasmas exposure of patient-derived primary glioblastoma tissue led to significantly decreased release levels of b-NGF, IL-6, sTREM2, TGF-β, TNF-α, and TREM-1." (PMID 35159079, 2022). "TREM1 expression was detected in three of five PDX cell lines and in the established U87-MG glioblastoma cell line." (PMID 36249290, 2022). "In vitro assays confirmed inhibition of cell fusion events and reduction of myeloid-derived cell migration towards glioblastoma cells by SRI42127 and TREM1 decoy peptide (LP17) versus control treatments." (PMID 36249290, 2022). "First, we defined the TREM1+-myeloid-derived microenvironment in the immunocompetent TRP and GL261 mouse glioblastoma models." (PMID 36249290, 2022). "TREM1 and ZNF395 expression were both mostly expressed in proximity of multilayered blood vessels of glioblastoma." (PMID 19536297, 2009). "It was revealed from a comprehensive analysis of TREM1 expression data obtained from The Cancer Genome Atlas Program (TCGA) and GTEx that TREM1 was highly expressed in the majority of cancers, including glioblastoma multiforme (GBM) and lower grade gliomas (LGG)." (PMID 38370418, 2024).
glioblastoma (continued). "RNA expression patterns for TREM1 and ZNF395 were analyzed in situ on glioblastoma sections." (PMID 19536297, 2009). "TREM1+-cells were enriched in poly-morphonuclear PMN (up to 75%) and Mφ (up to 15%) fractions, and at a lesser degree were observed in the microglia fraction (up to 3%) following three weeks of the tumor development (G for TRP and GL261 glioblastoma models, respectively)." (PMID 36249290, 2022). "TREM1 expression was significantly enhanced in the myeloid-derived (CD45+CD11b+) cells isolated from the dissociated brain tissue of mice harboring TRP and GL261 tumors compared to the control mice without intracranial tumor cells injection (F for TRP and GL261 glioblastoma models, respectively)." (PMID 36249290, 2022). "Finally, a critical role for TREM-1-expressing TAMs in pancreatic cancer progression was shown in xenograft mouse models (see Section 7 for details), and a TREM-1 increased expression was also observed in Mn from patients with invasive cervical cancer and in TAM infiltrating glioblastoma." (PMID 32456204, 2020). "However, neither under normoxia, nor hypoxia TREM1 expression was detectable in the glioblastoma cell-lines (data not shown), thus supporting the hypothesis that TREM1 is expressed by inflammatory cells." (PMID 19536297, 2009).
Stroke (15 papers, 2018 to 2025). Sudden impairment of blood flow to a part of the brain due to occlusion or rupture of an artery to the brain. "After a stroke, RNA sequencing showed an increase in genes associated with the TREM-1 and NLRP3 pathways, including Nfkb2 and IL-1β, which contribute to the neuroinflammatory response immediately after ischemia." (PMID 40867169, 2025). "Blocking TREM-1 in stroke models lowers infarct size, BBB leakage, and neuron loss." (PMID 41226426, 2025). "It is hypothesized that targeting TREM-1 treatment may reduce ischemic brain injury and stroke-associated infections." (PMID 36273145, 2022). "Thus, by regulating TREM1 activity in both the peripheral and central systems, it may be possible to diminish the inflammatory response, thereby reducing the damage caused by stroke." (PMID 38468280, 2024). "Additionally, TREM-1 activation in the intestine exacerbates intestinal epithelial permeability, thereby further contributing to bacterial translocation across the intestinal barrier, which is associated with the development of bacteremia after stroke." (PMID 36273145, 2022). "As the overexpression of TREM1 in microglia contributes to post-stroke neuroinflammatory damage, its expression in the microglia of tMCAO mice after SalC administration was investigated." (PMID 38468280, 2024). "This study suggests that elevated TREM-1 within 24 h of onset correlates with stroke severity and is an independent prognostic factor for stroke." (PMID 36273145, 2022). "However, whether the augmentation of neuroinflammatory markers in acute ischemic brain tissue by the activation of the TREM-1 signaling pathway, after acute ischemic stroke, is associated with stroke severity and predisposes patients to neurological deterioration is unclear." (PMID 33375339, 2020). "In detail, in experimental stroke, TREM-1 is up-regulated in myeloid cells within the spleen and intestine, from where it reaches the brain to magnify stroke injury." (PMID 31546668, 2019). "Consistently, robust TREM-1 positive cells co-stained with Iba-1 were detected 3 days post-stroke in peri-infarct zone, indicating a microglial autonomous increment of TREM-1 (p < 0.001)." (PMID 31324751, 2019). "Remarkably, novel studies unraveled that in experimental ischemia/stroke, a dramatic up-regulation of TREM-1 occurs firstly in the gut and subsequently in the CNS." (PMID 31546668, 2019). "This phenomenon is best exemplified by studies on the role of TREM-1 in stroke treatment." (PMID 39809747, 2025). "TREM-1 seems to be critically involved in activation of peripheral innate immunity resulting in recruitment of inflammatory cells to the brain after stroke and in parallel also in inflammatory damage of the gut-blood-barrier allowing bacterial translocation and infectious complications." (PMID 40295361, 2025). "This suggests that SalC may inhibit pro-inflammatory factors in microglia through the TREM1 pathway, thereby suppressing neuroinflammation and exerting a protective effect against stroke." (PMID 38468280, 2024). "TREM1 was recognized as the key role in the inflammatory response after stroke." (PMID 34721438, 2021). "TREM1 can recruit spleen tyrosine kinase (SYK) and interacting with SYK, which could launch downstream pro-inflammatory pathways after stroke, and inhibition of TREM1 could exert neuroprotective effects in stroke." (PMID 34721438, 2021). "Therefore, the post-stroke immune response offers an extended window for therapeutic intervention in acute ischemic stroke by targeting TREM-1 pathways." (PMID 33375339, 2020). "The protein level of TREM-1 remained significantly higher at 28 days post-stroke." (PMID 31324751, 2019). "However, whether the peripheral TREM-1 amplifies the stroke severity in patients after acute ischemic stroke is unknown." (PMID 33375339, 2020).
Stroke (continued). "Thus, following a stroke, peripheral TREM-1 induction may amplify pro-inflammatory responses to both brain-derived and intestinal-derived immunogenic components, while targeting TREM-1-reducing gut barrier dysfunction and stroke-related cerebral injury." (PMID 31546668, 2019). "TREM1 and TLR4 synergistically interact to enhance inflammatory responses, and co-activation is crucial for understanding the pathophysiology of stroke and potential therapeutic interventions." (PMID 38468280, 2024). "Remarkably, pharmacologic inhibition of TREM-1 with the synthetic peptide LP17 abrogated microglial M1 polarization and the activation of pyroptosis-related molecules, improving stroke outcomes." (PMID 38026442, 2023). "Blockade of TREM-1 can inhibit TREM-1/SYK pathway activation and subsequent inflammatory responses, rescuing stroke outcomes." (PMID 31324751, 2019). "Serum levels of TREM-1 and TREM-2 were found to be elevated in patients after stroke." (PMID 36273145, 2022). "Additionally, TREM-1 increases BBB permeability, facilitating the infiltration of peripheral immune cells and enhancing the expression of matrix MMP-9, which contributes to endothelial dysfunction and hemorrhagic transformation in stroke." (PMID 41226426, 2025). "Additionally, a number of studies have revealed that multiple pathways, such as nucleic acid-sensing cyclic GMP-AMP synthase (cGAS), nuclear factor-kappaB (NF-κB) and triggering receptor expressed on myeloid cells-1 (TREM-1), are involved in stroke via the activation of inflammasomes." (PMID 38026442, 2023). "However, to date, the precise role of TREM-1 and its downstream factors orchestrating post-stroke neuroinflammation has not been clarified." (PMID 31324751, 2019).
glioma (14 papers, 2009 to 2025). A benign or malignant brain and spinal cord tumor that arises from glial cells (astrocytes, oligodendrocytes, ependymal cells). "We then conducted GO and KEGG analysis to understand the main biological processes and pathways associated with TREM1 in whole glioma." (PMID 38370418, 2024). "Although TREM1 is considered to be a marker associated with M1 macrophages, high TREM1 expression is associated with poor survival among glioma patients." (PMID 35203505, 2022). "Our findings reveal that TREM1 expression is closely associated with the MES subtype of gliomas." (PMID 41394801, 2025). "There appears to be an association between TREM1 and a malignant phenotype and that it may be involved in glioma progression." (PMID 38370418, 2024). "To investigate the role of TREM1 in tumor progression *in vivo*, we established an orthotopic glioma model using GL261-luc cells and administered LP17 via intraperitoneal injection." (PMID 41394801, 2025). "TREM1 is preferentially expressed by M2-like TAMs and induces a mesenchymal-like state in glioma stem cells (GSCs) by modulating the secretion of TGFβ2, thereby activating the TGFβR/SMAD2/3 signaling pathway in GSCs." (PMID 41394801, 2025). "Our bioinformatics analysis further confirmed that TREM1 exerts anti-tumor effects in gliomas by targeting TLR4." (PMID 41394801, 2025). "Using a Transwell co-culture model with THP-1 cells in the upper chamber and glioma cells in the lower chamber, we investigated the role of TREM1 in the PMT process of GBM." (PMID 41394801, 2025). "By meticulously analyzing single-cell sequencing data in conjunction with the TCGA database, we identified that TAM cell populations with elevated TREM1 expression were correlated with a poorer prognosis in glioma patients." (PMID 41394801, 2025). "This study offers significant insights into the role and mechanism of TREM1 in the PMT transformation in glioma patients." (PMID 41394801, 2025). "TREM1 was notably enriched in glioma subtypes with higher malignant potential, particularly the MES subtype." (PMID 41394801, 2025). "Earlier findings from this research highlighted the involvement of TREM1 in TAM cells during the glioma PMT process." (PMID 41394801, 2025). "In summary, these data suggested TREM1 function as a contributor to remodeling the immunosuppressive microenvironment and promoting malignant progression of glioma." (PMID 38370418, 2024). "To date, there is no comprehensive report illustrating the immunosuppressive status with different TREM1 expression levels in glioma." (PMID 38370418, 2024). "The discrimination ability of TREM1 expression for mesenchymal subtype in all grade glioma was further assessed by Receiver operating characteristic curve (ROC) analysis." (PMID 38370418, 2024). "Patients with high TREM1 expression exhibited significantly shorter overall survival (OS) than their counterparts in pan-glioma analysis of TCGA and CGGA datasets." (PMID 38370418, 2024). "In our study, TREM1 was identified as a potential immune molecular target to further optimize immunotherapy for glioma." (PMID 38370418, 2024). "Here, we investigated the clinical, molecular, and immunological characteristics of TREM1 in glioma." (PMID 38370418, 2024). "Expression data from publicly available databases (TCGA RNA-seq, n = 667; CGGA RNA-seq, n = 693; CGGA microarray, n = 301; and GSE16011, n = 284) were further used to evaluate the expression levels of TREM1 mRNA in glioma of different WHO grades." (PMID 38370418, 2024). "A significant grade-dependent over-expression of TREM1 was confirmed in both low and high grades gliomas compared to normal brain samples utilizing the Madhavan study for brain tumors and Harris study for normal brain." (PMID 36249290, 2022).
glioma (continued). "Data from the Chinese Glioma Genome Atlas (CGGA) confirmed the highest TREM1 expression level in grade IV gliomas and a significant shortening of overall survival for patients harboring grade IV gliomas with TREM1 overexpression." (PMID 36249290, 2022). "TREM-1 and sTREM-1 expression were also recently assessed in 63 patients who underwent partial or complete resection of glioma (grade II, III and IV), in comparison to 31 healthy controls." (PMID 35875168, 2022). "Among them, ARHGDIB, LRRC25, PLAUR, and TREM1 were selected as prognostic hub genes in lower grade glioma in previous bioinformatic analyses." (PMID 34858984, 2021). "In 63 adult patients with gliomas and 31 healthy controls, the expressions of TREM-1 and TREM-2 on CD14+ blood cells (method: flow cytometry) and the levels of soluble sTREM-1, HMGB1, IL-6, and IL-10 (Elisa tests) were analyzed." (PMID 32684831, 2020). "The top five pathways associated with E2+CyP4 include (in order of statistical significance): mitochondrial function, amyloid processing, growth hormone signaling, TREM1 signaling, and glioma signaling." (PMID 22393359, 2012). "The hypoxia regulation of several new genes comprised in this cluster including ZNF395, TNFAIP3, and TREM1 was experimentally confirmed in glioma cell lines and primary monocytes exposed to hypoxia in vitro." (PMID 19536297, 2009). "The role of TREM1 in TAMs within the immunosuppressive TME of gliomas remains poorly understood." (PMID 41394801, 2025). "Furthermore, our rescue experiments employing the TLR4 agonist RS09TFA established that TLR4 activation can partially counteract the PMT suppression resulting from TREM1 inhibition in glioma." (PMID 41394801, 2025). "In vitro experiments substantiated the role of TREM1 in the proliferative and invasive processes of gliomas, demonstrating that TREM1 exerts its biological functions through the TLR4/PI3K/AKT/mTOR signaling axis, thereby facilitating the PMT transformation of glioma cells." (PMID 41394801, 2025). "We observed that TREM1 expression increased with the grade of malignancy in glioma." (PMID 38370418, 2024). "After blocking TREM1, glioma-derived TAMs expressed less levels of IL-6, IL-8, CCL2 and CCL8." (PMID 38370418, 2024). "All these findings collectively implied that TREM1 may serve as an independent prognostic biomarker for glioma patients." (PMID 38370418, 2024). "Although TREM1 inhibitors are currently unavailable for clinical application, a desirable relationship between TREM1 and other immune checkpoints maps out a rosy blueprint for the combination therapy of glioma." (PMID 38370418, 2024). "Considering the substantial link between TREM1 and monocytes, we tested whether glioma cells can regulate the expression of TREM1 on monocytes." (PMID 38370418, 2024). "In summary, TREM1 may be a potential independent prognostic factor and immune target, which might provide new avenues to improve the efficacy of immunotherapy in glioma patients." (PMID 38370418, 2024). "In conclusion, our study illustrated that TREM1 as a potential independent prognostic factor and immune target that may improve clinical efficacy in glioma treatment." (PMID 38370418, 2024). "In addition, our study suggested higher TREM1 expression levels predicted worse survival among patients with glioma, especially GBM." (PMID 38370418, 2024). "Taking these findings together, TREM1 may play an important role in immunobiologic processes of glioma." (PMID 38370418, 2024). "The TREM-1/TREM-2 ratio that expression on the surface of blood monocytes could help predict prognosis in patients with gliomas." (PMID 34176389, 2021). "We showed that the TREM-1/TREM-2 ratio (expression on the surface of blood monocytes) could help predict prognosis in patients with gliomas, especially in high-grade gliomas, and that systemic inflammation has an impact on the patient's overall survival." (PMID 32684831, 2020).